WT1 (WT1 transcription factor)
Diseases named in the same sentence as WT1 in open-access papers (continued):
Sharing a sentence is not in itself a finding about the gene and the disease.
leukemia (continued). "In recent years, the study of WT1′s involvement in malignant cells has unexpectedly revealed a potential role for WT1 as an oncogene, especially in leukemia." (PMID 32178481, 2020). "Regenerated CTLs were able to prolong the survival of mice in a xenograft leukemia model, where WT1-expressing human leukemia cells were inoculated into immunodeficient mice followed by transfusion of regenerated WT1-CTLs." (PMID 33102617, 2020). "Treatment with 2.5 μM concentration of WP1130 resulted in decreased levels of WT1 protein, and treatment with 5.0 μM concentration of WP1130 resulted in almost complete loss of WT1 in leukemia cell lines (left blots)." (PMID 32580769, 2020). "Analyzing mRNA expression of BCR/ABL and WT1 of ocular fluid in patients with hypopyon is beneficial in diagnosing topical relapses in leukemia." (PMID 31977890, 2020). "These regenerated CTLs were able to prolong the survival of mice in a xenograft leukemia model where WT1-expressing human leukemia cells were inoculated into immunodeficient mice followed by transfusion of the WT1-specific regenerated CTLs (WT1-CTLs)." (PMID 32259478, 2020). "As aberrant expression of WT1 in leukemia is the most consistent finding, several studies addressing the role of WT1 in leukemia have been reported." (PMID 33110919, 2020). "WT1 gene silencing in these leukemia cells resulted in growth inhibition and enhanced apoptosis and decreased S phase fraction." (PMID 33110919, 2020). "For example, overexpression of WT1 combined with AML1-ETO/RUNX1-RUNX1T1 rapidly induces murine leukemia." (PMID 32580769, 2020). "Our results indicate that knockdown of wt1 substantially decreases the frequency of LSC, impairs LSC self-renewal ability, and prolongs the overall survival in MLL-AF9-induced murine leukemia, suggesting that WT1 is required for the development of leukemia." (PMID 32580769, 2020). "Aberrant expression of wild-type WT1 was detected in various malignancies, especially breast cancer, ovarian cancer, hepatocellular carcinoma, leukemia, and neuroepithelial tumor." (PMID 33110919, 2020). "WT1 is a possible antigen to specifically target in leukemia patients as it was demonstrated that WT1-reactive cytotoxic T-cells mediate a strong anti-tumor immune response in post-transplant patients." (PMID 32604862, 2020). "The results showed that the expression of IL-2RG and IL-2RB mRNAs was decreased until reaching an undetectable level at 48 and 72 hours posttransduction, respectively, in K562-WT1-siRNA-GFP+ (WT1-siRNA) leukemia cells." (PMID 33110919, 2020). "We further pursued an apoptotic assay to evaluate the possible role of WT1 in the apoptosis regulation of leukemia cells." (PMID 33110919, 2020). "WT1 is thought to be one of the markers for leukemia, and that can be used for predicting prognosis and monitoring relapse." (PMID 31977890, 2020). "Another approach is vaccinating using BCG-CWS plus WT1 peptide also expressed in leukemia, which demonstrated that mycobacteria components increase WT1-specific immune responses, favoring rejection of WT1-expressing leukemia cells." (PMID 32635668, 2020). "Our results are in line with some previous reports showing that downregulation of WT1 by using antisense oligonucleotides led to inhibition of cellular proliferation of K562 and fresh leukemia cells from AML and CML patients." (PMID 33110919, 2020). "WT1 is highly expressed in the bone marrow or the peripheral blood of a variety of leukemia in comparison to normal bone marrow and normal progenitor cells." (PMID 32178481, 2020). "Currently, WT1 vaccines against leukemia, breast cancer, lung cancer, and pancreatic cancer are undergoing phase I or II clinical trials, and their efficacy and adverse reactions are also being under investigation." (PMID 32210734, 2020). "In a xenograft mouse model, it was shown that WT1-siTCR/CD4+ T cells migrate to leukemia sites and subsequently attract WT1-siTCR/CD8+ T cells via chemotaxis." (PMID 30622438, 2019).
leukemia (continued). "Western blots for AML1‐ETO and WT1 in BM cells from leukaemia mice and normal mice demonstrate the successful transfection of AML1‐ETO and WT1." (PMID 31119862, 2019). "Based on a wide range of investigation of WT1-TCR-T cells, recently, the first clinical trial using WT1-TCR-modified T cells for leukemia therapy was reported." (PMID 30622438, 2019). "The focus was on the immunogenic leukemia antigen WT1, the streptamer technology was employed and a 60-fold increase in WT1-specific CD8+ effector T cells after positive selection by magnetic cell separation was found." (PMID 31878060, 2019). "Wilms tumor 1 (WT1) oncoprotein is an intracellular oncogenic transcription factor which is barely expressed in normal adult tissues but over expressed in a variety of leukemias and solid cancers." (PMID 31408937, 2019). "WT1 gene, although it is a suppressor gene in kidney tumors, acts as an oncogene in leukemia, lung cancer, breast cancer, and glioblastoma." (PMID 31024927, 2019). "Wilms tumor 1 (WT1) oncoprotein is a transcription factor that is rarely expressed in normal adult tissues but overexpressed in a wide range of leukemia and solid tumors, particularly in mesothelioma, glioblastoma, gastrointestinal cancer, and ovarian cancer." (PMID 31408937, 2019). "The BASP1 gene is downregulated in many human tumor cell lines particularly in those derived from leukemias, which display elevated levels of WT1 and of the major cancer driver MYC." (PMID 31058089, 2019). "T cells genetically modified to recognise WT1-28z specifically targeted and lysed HLA-A*02:01+ WT1+ tumours and improved the survival of mice engrafted with HLA-A*02:01+, WT1+ leukaemia cells." (PMID 30678059, 2019). "WT1 is a transcription factor used as a molecular marker for the monitoring of minimal residual disease in leukemia, especially in myeloid leukemias and myelodysplastic syndrome." (PMID 31035598, 2019). "Comparing the gene expression profiles between leukemia cells and normal human hematopoietic cells, only WT1 and PRAME expression was significantly higher in leukemia cells compared to normal human hematopoietic cells, in CML only PRAME." (PMID 31575892, 2019). "Recently, the first clinical trial using Wilms’ tumor gene product 1 (WT1)-TCR-modified T cells for leukemia immunotherapy has been reported." (PMID 30622438, 2019). "WT1-siTCR/CD4+ T cells sufficiently recognized leukemia cells in an HLA class I-restricted manner and provided target-specific Th1 help for WT1-siTCR/CD8+ T cells." (PMID 30622438, 2019). "Weber and colleagues generated autologous T-cell lines from ALL patients by targeting the tumor-associated antigens WT1, MAGE-A3, Survivin, and PRAME, which were able to specifically kill autologous leukemia blasts in vitro." (PMID 30678050, 2019). "To further dissect the function of leukemia-reactive CD73− CD8 T cells, we examined CD8 T cells for cytokine release in response to WT-1, which is a well-known tumor-associated antigen." (PMID 31014364, 2019). "For example, WT1 is constitutively expressed in myeloid leukemia cells, including acute myelocytic leukemia (AML) and CML, and myelodysplastic syndrome (MDS), and WT1-specific CTLs have been identified in blood from leukemia patients." (PMID 30622438, 2019). "Mutations in other common leukemia-related genes such as nucleophosmin 1 (NPM1), CCAAT/enhancer-binding protein alpha (CEBPA), and Wilms tumor 1 (WT1) have been found to occur as both preleukemic and late events." (PMID 29164062, 2017). "WT-1 specific T cells generated from normal HSCT donors were administered at escalating doses (3.8 × 108 to 3.3 × 109/m2) to 11 patients with WT-1+ leukaemia, MDS, or myeloma in disease relapse post-transplantation." (PMID 28635677, 2017). "The WT1 gene is overexpressed in leukemia and a variety of solid tumors, in which it exerts an oncogenic function." (PMID 28116121, 2016).
leukemia (continued). "TET2 binds and activates WT1 target genes by increasing the 5hmC levels at the promoter regions of these specific sites in normal HSC, and therefore TET2 inhibits leukemia proliferation in a WT1-dependent manner." (PMID 26861406, 2016). "The aim of this study was to comparatively analyze the predictive impact of sequential MRD monitoring with leukemia‐associated immunophenotypes (LAIP)‐MFC and WT1 Q‐PCR in a cohort of 104 consecutively treated AML patients." (PMID 26715369, 2016). "Low levels of WT1 protein expressions have been found in normal blood cells, while high levels of WT1 protein have been found in leukemia patients." (PMID 27193767, 2016). "Their findings provide a strong basis for the planned WT1-TCR gene therapy trials of leukemia patients." (PMID 27818694, 2016). "WT1 codes for a transcriptional factor recurrently mutated in AML, but with a still unclear role in leukemia development." (PMID 27462774, 2016). "The results of the present study demonstrate that mammea E/BB inhibited cell proliferation and repressed WT1 expression in the human leukemia K562 cell line." (PMID 27193767, 2016). "All major WT1 isoforms are overexpressed in leukemia and solid tumors and play oncogenic roles such as inhibition of apoptosis, and promotion of cell proliferation, migration and invasion." (PMID 26090994, 2015). "It has been shown that all major WT1 isoforms are overexpressed in leukemia and solid tumors, where different major isoforms have different oncogenic functions." (PMID 26090994, 2015). "WT-1 regulates the oncogenicity of leukemia cells by activating JAK/STAT3 and MAPK signaling, therefore we explored the role of JAK/STAT3 and MAPK signaling in the WT1-mediated resistance to DOX." (PMID 26462627, 2015). "Wilms’ tumor 1 (WT1) represents the most potent tumor-associated antigen widely detected in cancer, sarcoma, and leukemia in terms of therapeutic function, immunogenicity, specificity, and oncogenicity." (PMID 26690485, 2015). "Expanded CTLs showed antigen-specific reactivity against WT1 and against the primary WT1+ leukemia cells." (PMID 28548069, 2014). "WT1 seems to be an oncogenic protein involved in transcriptional regulation in leukemogenesis and for the viability of leukemia blasts 29–31." (PMID 24715586, 2014). "WT1 is overexpressed in the majority of leukemia and various types of tumors such as lung, colorectal and pancreatic cancer, and glioblastoma multiforme." (PMID 24589652, 2014). "Intriguing, an early trial by using peptide vaccines against WT1 in leukemia patients did show promising results." (PMID 24667279, 2014). "Because WT1 is expressed in leukemia cells, the development of cancer immunotherapy targeting WT1 has been an attractive translational research topic." (PMID 24393438, 2014). "sgRNA can be easily taken up by cultured cells without any transfection reagents, and naked sgRNAs targeting Bcl2 or WT1 mRNA can reduce the mRNA level and the amount of protein as well as inducing apoptosis of leukemia cells." (PMID 25437003, 2014). "Many studies have shown that the wild-type WT1 gene is expressed in leukemia, breast cancer, lung cancer, ovarian cancer, mesothelioma, renal cell carcinoma, and bone and soft tissue sarcomas." (PMID 25026998, 2014). "Studies have demonstrated that IgM and/or IgG antibodies against WT1 were detectable at a higher level in sera in patients with leukemia and myelodysplastic syndrome (MDS) compared with healthy individuals 33,36." (PMID 24715586, 2014). "Gammaretroviral vectors were introduced into T cells to encode the α and β TCR chains forming a TCR specific for the melanoma antigen MART1, CEA (for colorectal carcinoma), NY-ESO-1 (melanoma), WT1 (leukemia), and CMV pp65 (for EBV treatment)." (PMID 25490763, 2014).
leukemia (continued). "Silencing of WT1 causes decreased proliferation and viability in most cancer cell lines including K562 and MM6 leukemia, MCF-7 breast cancer, A549 lung cancer, B16F10 melanoma lung metastasis, and U251MG human multiform glioblastoma." (PMID 25474318, 2014). "Mutations in WT1 have been reported in 6-10% of AML cases, 20% of biphenotypic leukemias and sporadic T-cell acute lymphoblastic leukemias (T-ALL)." (PMID 24405639, 2014). "Because WT1 is expressed in leukemia cells, including leukemia stem cells, the development of cell-mediated immunotherapy targeting WT1 has been an attractive translational research topic." (PMID 24393438, 2014). "Spontaneous autologous T-cell responses against WT-1 can also be detected in the peripheral blood of leukemia patients, providing rationale for either allogeneic or autologous ACT approaches." (PMID 26056592, 2014). "WT1 has been identified as a potential molecular target for leukemia and some solid tumors, studies also demonstrated a correlation between WT1 expression and overall patient survival." (PMID 24228711, 2013). "The Wilms’ tumor suppressor gene (WT1) has been identified as an oncogene in many malignant diseases such as leukaemia, breast cancer, mesothelioma and lung cancer." (PMID 23936312, 2013). "Other attractive LAAs, including WT1 antigen, proteinase-3 peptide, PRAME, and RHAMM, which are self-antigens overexpressed in leukemia cells, can also serve as leukemia-associated targets for immune responses." (PMID 23394714, 2013). "The CTLs develop after just 7 days’ stimulation without exogenous cytokine supplementation and lyse MHC-restricted targets, including primary WT1-expressing blasts from leukemia patients." (PMID 23837662, 2013). "Several leukemia-associated antigen targets are being explored for CTL mediated therapy, for example the Wilms tumor-1 (WT1) gene product." (PMID 23847759, 2013). "WT1 (Wilms tumor antigen) is involved in leukemogenesis and is overexpressed in all types of leukemia." (PMID 31803284, 2012). "The WT1 gene was originally defined as a tumor suppressor gene, but recent studies suggest that the WT1 gene is highly expressed in leukemia and solid tumors and likely plays an oncogenic role in leukemogenesis and tumorigenesis." (PMID 21980425, 2011). "WT1 is expressed in many adult tumors, of which leukemia has received particular attention due to the strong association between WT1 expression posttreatment and poor prognosis." (PMID 20122399, 2010). "Wilms tumor protein (WT1) is a transcription factor selectively overexpressed in leukemias and cancers; clinical trials are underway that use altered WT1 peptide sequences as vaccines." (PMID 19079589, 2008). "WT1 peptides as vaccine for anti-leukemia immunotherapy will be evaluated in our local patients in the future." (PMID 19662212, 2007). "Recent findings point to an oncogenic effect of WT1 in tumor types such as leukemia and breast cancer." (PMID 19455234, 2007). "Studies in recent years by a number of reports have demonstrated that the WT1 protein-induced specific anti-leukemia activity by cytotoxic T lymphocytes (CTL) was HLA-A2-restricted." (PMID 19662212, 2007). "The anti-leukemia activity of WT1-induced CTLs are reported to be HLA-A restricted and has been used as adoptive immunotherapy in some small scale clinical trials in patients with acute leukemia." (PMID 19662212, 2007). "Many leukemia cell lines express high levels of wild-type WT1 mRNA, for example, NB4 and K562." (PMID 40613901, 2025). "Also important, ST2 deficiency in Tregs or treatment with neutralizing anti-ST2 Abs early during leukemia restores WT1+CD8+ T cells in the TME." (PMID 40691440, 2025). "As a result, multiple clinical trials exploiting WT1 have been conducted in leukemia." (PMID 40847198, 2025). "However, in contrast to this suppressive role, WT1 is marked upregulated in the BM and PB of leukemia patients, highlighting its oncogenic potential in pathological settings." (PMID 40507300, 2025).
leukemia (continued). "WT1 presents several characteristics of an ideal target antigen for immunotherapies; it is highly expressed in leukemia cells, compared to normal cells, and leukemia cells rely on its continuous expression making tumor escape through antigen loss unlikely." (PMID 40847198, 2025). "We additionally chose to generate the classifier for two common HLA-A:02*01 restricted WT1 epitopes, although leukemia cells may present additional epitopes, thus we potentially missed naturally occurring immune responses against these additional epitopes." (PMID 40847198, 2025). "The hypothesis that treatment when only a lower burden of tumor is present is attractive because the TME ratio of CD8 T cells to ST2+ Treg cells, and to MLL-AF9 cells, will be favorable for antigen-specific WT1+CD8+ T cells to be able to kill the leukemia." (PMID 40691440, 2025). "Future studies are warranted to assess if the therapeutic targeting of the WT1/SGK1 pair could help induce leukemia cell maturation or apoptosis." (PMID 40613901, 2025). "Notably, cytotoxic T lymphocytes (CTLs) specific to WT1 have been recognized in the blood of leukemia patients." (PMID 39411712, 2024). "However, WT1 gene was highly expressed in leukaemia, BRCA and many other tumours with an oncogenic role." (PMID 39169452, 2024). "Wilms tumor antigen 1 (WT1) is a transcription factor overexpressed in some leukemias." (PMID 39512351, 2024). "WT1 is also an important immunotherapeutic target, with several WT1-directed therapies shown to be safe and demonstrating antineoplastic activity in early clinical trials for leukemias and solid tumors." (PMID 38190392, 2024). "However, the binding profile of EWSR1::WT1 in DSRCT differs significantly from WT1 in leukemia cells." (PMID 39139449, 2024). "Moreover, WT1 vaccination is being studied in combination with immune checkpoint inhibitors in patients with relapsed or refractory solid tumors and leukemias (ClinicalTrials.gov, NCT03761914)." (PMID 38190392, 2024). "Since WT1 or DNMT3A mutations are presented in only 20.5% patients with CEBPAbZIP-inf who had relapsed, it’s apparent that non-genetic drivers underpin a large proportion of functional variation in leukemia." (PMID 38253683, 2024). "However, high levels of WT1 protein expression have already been documented in some leukemias and almost all types of solid adult tumors." (PMID 38929778, 2024). "Moreover, the WT1126 epitope is not a suitable target for T cell-based immunotherapy due to its low presentation on MHC-I, despite the high expression of WT1 antigen in leukemia cells." (PMID 39116074, 2024). "We sought to determine if the major WT1 isoforms overexpressed in leukemias and multiple solid tumors, which occur as a result of alternative splicing at Exon 5 and Exon 9 (WT1 isoforms A [EX5-/KTS-], B [EX5+/KTS-], C [EX5-/KTS+] and D [EX5+/KTS+] are also overexpressed in primary KS lesions." (PMID 38190392, 2024). "These four major WT1 isoforms are overexpressed in solid tumors and leukemias, having varying oncogenic functions that promote cellular proliferation, survival, angiogenesis, cell migration and invasion, anti-apoptotic actions, and contribute to epithelial to mesenchymal transition." (PMID 38190392, 2024). "Thus, the highest-avidity TCR, S117A-TCR should be the most promising TCR for developing CD4+ T cell-based adoptive T cell therapy against HLA class II-positive WT1-expressing malignancies, such as leukemia." (PMID 36939853, 2023). "Importantly, we demonstrated that transduction of an avidity-maturated TCR conferred strong cytotoxicity against WT1-expressing leukemia cells on CD4+ T cells, compared to that of its original TCR." (PMID 36939853, 2023).